RN7SKP144 (RN7SK pseudogene 144)
Gene: Miscellaneous RNA gene on chromosome 3 (2,088,933 to 2,089,211, reverse strand). Ensembl gene ENSG00000223040.
Homologues: Orthologues: chimpanzee 7SK (97% identical). Paralogues in human: RN7SKP255 (81% identical), RN7SKP203 (80% identical), RN7SKP180 (80% identical), RN7SKP80 (80% identical), RN7SKP9 (80% identical), 7SK (79% identical), RN7SKP231 (79% identical), RN7SKP79 (79% identical), RN7SKP90 (79% identical), RN7SKP95 (79% identical), RN7SKP1 (78% identical), RN7SKP124 (78% identical), and 284 more.